TAX1BP1 (Tax1 binding protein 1)
Diseases named in the same sentence as TAX1BP1 in open-access papers (continued):
Sharing a sentence is not in itself a finding about the gene and the disease.
cancer (10 papers, 2012 to 2025). A tumor composed of atypical neoplastic, often pleomorphic cells that invade other tissues. "TAX1BP1 is an autophagy cargo adaptor and also regulates apoptosis induced by protein synthesis inhibitors or DNA-damaging agents in cancer cells." (PMID 36795483, 2023). "TAX1BP1 (Tax1 binding protein 1) is a protein highly and specifically expressed in brain and has dual roles in modulating the destinies of cancer cells." (PMID 37186123, 2023). "The expression of TAX1BP1 was significantly associated with most HOXA family genes across cancers, but not in normal tissues." (PMID 33816499, 2021). "Similarly, there is downregulation of OTUD7B and TAX1BP1 in various cancers, which greatly contributes to hyperactivation of NF-κB signalling." (PMID 25595906, 2015). "In the autophagy mediated by copper and erastin (a ferroptosis inducer), the autophagy receptors TAX1BP1 and SQSTM1 can promote the degradation of GPX4, effectively reducing the resistance of cancer cells to ferroptosis." (PMID 41323827, 2025). "To confirm this, we focused on autophagy cargo receptors TAX1BP1 and BNIP3 because they have known proapoptotic effects in cancer cells." (PMID 36795483, 2023). "Interestingly, TAX1BP1 may regulate intestinal tumourigenesis in mouse models of cancer." (PMID 23209807, 2012). "Furthermore, it examines the molecular mechanism by which the autophagy receptors TAX1BP1 and SQSTM1 induce GPX4 degradation and impair cancer cell resistance to ferroptosis during copper‐ and erastin‐mediated autophagy processes." (PMID 41323827, 2025). "An antibody specific for PDIA4 co-immunoprecipitated TAX1BP1, while an antibody specific for TAX1BP1 co-immunoprecipitated PDIA4, according to our findings, PDIA4 acted as a binding partner for TAX1BP1 in TNBC cells and cancer specimens." (PMID 38167446, 2024).
infection (9 papers, 2015 to 2025). The state of being infected such as from the introduction of a foreign agent such as serum, vaccine, antigenic substance or organism. "At 24 hours post-infection, Tax1bp1-deficiency slightly increased Mtb colocalization with ubiquitin by 16%, whereas Tax1bp1-deficiency decreased Mtb colocalization with LC3 by 26%." (PMID 41171885, 2025). "Only when stimulated with IFN-γ, Tax1bp1-deficiency accelerated apoptotic cell death during Mtb infection of BMDMs on day 4 post-infection." (PMID 41171885, 2025). "During infection of BMDMs, we previously observed that Tax1bp1-deficiency enhanced ubiquitin colocalization with Mtb." (PMID 41171885, 2025). "Tax1bp1-deficiency increased Mtb growth during ex vivo infection of BMDMs, presumably because of the role of Tax1bp1 in antibacterial autophagy." (PMID 41171885, 2025). "The mean expression of TAX1BP1(as measured by exonic RPM) in MA-EBOV infected mouse livers (susceptible CC strains 5 days post infection) was 1.6 times greater than in the mock treatment (single-end reads mapped)." (PMID 39226335, 2024). "In addition to inducing inflammatory signaling during infection ex vivo, we discovered that Tax1bp1-deficiency initially reduces necrotic-like cell death in the first four days of Mtb infection in AMs but not BMDMs." (PMID 41171885, 2025). "In IFN-γ stimulated AMs, Tax1bp1-deficiency accelerated apoptosis on day 3 post-infection." (PMID 41171885, 2025). "To assess the role of Tax1bp1’s contribution to controlling tuberculosis infection in vivo, we infected wild-type and Tax1bp1-deficient mice with virulent M. tuberculosis via the aerosol route and monitored the infection at different time points." (PMID 39763950, 2024). "Indeed, the possible effects of Tax1bp1-deficiency on other cell types may play an important role in contributing to host mortality during later stages of infection and disease." (PMID 41171885, 2025). "This analysis of three independent experiments indicates that Tax1bp1-deficiency can enhance Mtb growth in MNC1 and neutrophils at 21-days post-infection, which is consistent with our previous CFU analysis in BMDMs infected ex vivo." (PMID 41171885, 2025). "Tax1bp1-deficiency reduced ZsGreen+ Mtb counts in AMs, MNC1, and MNC2 at 14 days post-infection and in AMs at 28 days post-infection." (PMID 41171885, 2025). "To examine the role of Tax1bp1 in controlling Mtb growth, we harvested the lung, spleen, and liver of wild-type and Tax 1bp1-/- mice on days 9 or 11, 21, and 50 post-infection and quantified bacterial CFUs." (PMID 41171885, 2025). "Tax1bp1-deficiency reduced CD8+ T cell recruitment by 2 and 2.5-fold at 21- and 28-days post-infection, respectively." (PMID 41171885, 2025). "The autophagy receptor Tax1bp1 plays a role in multiple stages of intracellular pathogen infections, including autophagy and regulation of cytokine responses." (PMID 39763950, 2024). "In two independent aerosol infection experiments, Tax1bp1 enhances Mtb growth in AMs, PMNs, and MNC2, boosting Mtb growth in immune cells of various cell origins in vivo." (PMID 39763950, 2024). "Tax1bp1 also leads to increases in bacterial growth and inflammatory responses during infection of mice with Listeria monocytogenes, an intracellular pathogen that is not effectively targeted to canonical autophagy." (PMID 39763950, 2024). "During infection of BMDMs, we previously observed that Tax1bp1 reduces ubiquitin colocalization with Mtb." (PMID 39763950, 2024). "To our knowledge, we are the first to study the function of Tax1bp1 in the context of mouse infections with these pathogens." (PMID 39763950, 2024). "To expand our understanding of Tax1bp1’s function in other critical innate immune cell types and the presence of the complete immune system, here we employed the mouse infection models for Mtb and the intracellular pathogen Listeria monocytogenes." (PMID 39763950, 2024).
infection (continued). "We initially discovered that Tax1bp1 is significantly phosphorylated during Mtb infection compared to mock infection at the IKKα substrate serine-693 in a global phosphoproteomic analysis of BMDMs." (PMID 39763950, 2024). "At 24 hours post-infection, Tax1bp1 slightly decreased Mtb colocalization with ubiquitin by 16%, whereas Tax1bp1 increased Mtb colocalization with LC3 by 26%." (PMID 39763950, 2024). "Tax1bp1 restricts Mtb growth during ex vivo infection of BMDMs presumably because of the role of Tax1bp1 in antibacterial autophagy." (PMID 39763950, 2024). "Our results suggest that ebola virus disease can increase expression of TAX1BP1 in the mouse MA-EBOV system (Day five post infection)." (PMID 39226335, 2024). "Infection of alveolar macrophages isolated from TAX1BP1 knockout mice resulted in enhanced secretion of antiviral and inflammatory cytokines compared to RSV-infected macrophages isolated from wild-type mice." (PMID 35216012, 2022). "Because galectin-8 itself is likely ubiquitinated during infection, we predicted that TAX1BP1 would bind to galectin-8 via its UBZ domains." (PMID 34225486, 2021). "We observed a moderate yet statistically significant increase in Mtb CFUs at 3- and 5 days post-infection in Tax1bp1-/- macrophages compared to wild-type controls." (PMID 31951200, 2020). "In contrast to the bimodal peak in overall host protein phosphorylation early (2–4 hr) and late (24 hr) after infection, autophagy receptor phosphorylation, including TAX1BP1, was greatest in between these two peaks (6–8 hr)." (PMID 31951200, 2020). "Internalised Salmonella were harvested from HeLa cells at 2, 4, or 8 hours post-infection in mock and myosin VI or TAX1BP1/NDP52/optineurin (TNO) siRNA depleted cells and the fold replication of Salmonella was measured." (PMID 26451915, 2015). "Therefore, we focused on understanding Tax1bp1’s function in AMs as this model better represents the overall impact of Tax1bp1 on real-world infections." (PMID 41171885, 2025). "In the absence of IFN-γ stimulation, Tax1bp1-deficiency led to a modest decrease in necrotic-like cell death of AMs on days 1–4 post-infection." (PMID 41171885, 2025). "As with the IV infection, Tax1bp1-deficiency led to a considerable non-statistically significant decrease in IL-6 production and a substantial decrease in IFN-γ in the serum." (PMID 41171885, 2025). "Since Tax1bp1 restricted Mtb growth in BMDMs infected ex vivo but the opposite phenotype was observed during in vivo mouse infections, we hypothesized that Tax1bp1 promotes Mtb growth in other cell types." (PMID 39763950, 2024). "This is consistent with the role of Tax1bp1 being manifested at the earliest stages of infection." (PMID 39763950, 2024). "Therefore, we focused on understanding Tax1bp1’s function in AMs as this model better represents the overall impact of Tax1bp1 on real-world infections and in most innate immune cell types." (PMID 39763950, 2024). "A better understanding of the mechanism by which Tax1bp1 regulates host cell death, autophagy, and inflammation during infection may enable the development of Tax1bp1 as a target for anti-bacterial therapies." (PMID 39763950, 2024). "Four receptors (BNIP3L, Optineurin, FUNDC1, and TAX1BP1) were selectively modified upon Mtb infection; these modifications occurred in functional domains of these receptors and changed through the time course of infection." (PMID 31951200, 2020). "To test if TAX1BP1 mediates cell-intrinsic resistance to Mtb growth, we infected bone-marrow-derived macrophages with wild-type Mtb at a multiplicity of infection of 1 and enumerated colony-forming units (CFUs) on days 0, 3, and 5 post-infection." (PMID 31951200, 2020).
infection (continued). "These experiments revealed that Tax1bp1 protein abundance does not significantly change early after infection in AMs but does in BMDMs; moreover, early after infection, Tax1bp1-deficiency reduced necrotic-like cell death -- an outcome that favors Mtb replication -- in AMs but not BMDMs." (PMID 41171885, 2025). "In addition to decreasing neutrophil recruitment, Tax1bp1-deficiency increased MNC1 recruitment at 28 days post-infection but had no impact on MNC2 recruitment." (PMID 41171885, 2025). "Given that hyperinflammatory responses promote Mtb infection, we reasoned TAX1BP1 may also function to limit these responses, especially since we identified increased TAX1BP1 phosphorylation at Ser-693, a substrate for IKKα, during infection." (PMID 31951200, 2020). "One possible explanation for the discrepancy between changes in Mtb growth caused by Tax1bp1-deficiency and the lack of major Mtb transcriptional changes is that our transcriptional profiling was performed before significant changes in Mtb growth were observed, beginning at 48 hours post-infection." (PMID 41171885, 2025). "Consistent with the ZsGreen+ counts, Tax1bp1 promoted Mtb growth by CFU counts in AMs by 11-fold and in PMNs by 6-fold at seven days post-infection." (PMID 39763950, 2024). "Tax1bp1 protein level did not change significantly during Mtb infection of AMs but did increase significantly during BMDM infection, highlighting a potential mechanism that explains the different responses mediated by Tax1bp1 in BMDMs and AMs." (PMID 41171885, 2025). "Using this more sensitive approach revealed (i) decreased neutrophil recruitment and (ii) increased proportions of live AMs at 28 days post-infection in mice lacking Tax1bp1." (PMID 41171885, 2025). "We found that Tax1bp1-deficiency reduced necrotic-like cell death and inflammatory mediator release during AM but not BMDM infection, which is a likely mechanism by which Tax1bp1 leads to cell type-specific changes in Mtb growth." (PMID 41171885, 2025). "Although Tax1bp1 increases ZsGreen+ counts in MNC1 at 14-days post-infection, Tax1bp1 did not enhance Mtb CFU in MNC1 but did slightly in MNC2 (1.6-fold)." (PMID 39763950, 2024). "In Mtb-infected AMs but not BMDMs, Tax1bp1 enhances necrotic-like cell death early after infection, reprogramming the mode of host cell death to favor Mtb replication in AMs." (PMID 39763950, 2024). "As reflected by changes in luminescence, Tax1bp1 began to promote Mtb growth at two days post-infection in the presence or absence of IFN-γ." (PMID 39763950, 2024). "Importantly, these cytokine and eicosanoid levels were measured early after infection (24 hours) when the Mtb CFU were the same in wild-type and Tax1bp1−/− AMs, before any differences in Mtb growth were observed at later time points." (PMID 39763950, 2024). "As with the IV infection, Tax1bp1 led to a considerable non-statistically significant increase in IL-6 production and a substantial increase in IFN-γ in the serum." (PMID 39763950, 2024). "Our findings from the animal infection model led us to uncover new relevant phenotypes compared to those revealed by the BMDM infection model and revealed Tax1bp1’s negative impact on immunity to intracellular pathogens." (PMID 39763950, 2024). "Second, downregulation of A20, TAX1BP1 and ABIN1 decreased virus production at later times post-infection, and this may have contributed to reducing the intracellular immune response at this time." (PMID 32102364, 2020). "The absence of Tax1bp1 reduces Mtb growth during acute and chronic stages of animal infection." (PMID 41171885, 2025). "Together with the decreased cytokine production and lack of pulmonary histopathologic changes mediated by Tax1bp1-deficiency, the reduced CD8+ T cell and neutrophil recruitment indicates that Tax1bp1-deficiency abrogates systemic inflammatory responses during infection." (PMID 41171885, 2025).
infection (continued). "A mechanistic difference between Mtb-infected AMs and BMDMs that may contribute to these phenotypes is that Tax1bp1 protein abundance increased in BMDMs but not AMs following infection." (PMID 41171885, 2025). "In addition to inducing inflammatory signaling, we discovered that Tax1bp1 controls the mode of host cell death by initially promoting necrotic-like cell death in the first four days of Mtb infection in AMs but not BMDMs, while delaying apoptosis in the later stages of infection." (PMID 39763950, 2024). "We found that Tax1bp1 enhances necrotic-like cell death and inflammatory mediator release during AM but not BMDM infection, which is a mechanism by which Tax1bp1 leads to cell type-specific changes in Mtb growth." (PMID 39763950, 2024). "Gene silencing showed that downregulation of A20, TAX1BP1, ABIN1, and ITCH but not RNF11, increased apoptosis in cells infected with HRSV at later times post-infection." (PMID 32102364, 2020).
tumor (8 papers, 2010 to 2025). "Both miRNAs have been shown to limit inflammation and to restrain tumor growth, whereas the oncogenic miR-92, which promotes inflammation and tumor progression was overexpressed in Tax1BP1−/− mice." (PMID 33004985, 2020). "Additionally, the autophagy receptor TAX1BP1 mediates K63-linked ubiquitination of STING at Lys224, triggering its autophagic degradation to dampen immunotherapy efficacy; targeting this TAX1BP1-STING axis thus emerges as a promising approach to restore anti-tumour immunity." (PMID 41463025, 2025). "In this study, multiple experimental models and primary tumor samples demonstrated that aggregated protein, TAX1BP1, and NDP52 may be sensitive markers for assessing lysosomal degradation of autophagic cargo for preclinical studies and clinical trials utilizing lysosomal neutralizing agents." (PMID 32541677, 2020). "More importantly, single‐cell sequencing data supported that TAX1BP1 is highly expressed exclusively in clusters 3, while lactylation level, VIRMA and SP1 were highly expressed in tumor cells." (PMID 41017455, 2025). "In mice bearing human U87 tumor xenograft, administration of DPT (10 mg· kg−1 ·d−1, i.p., for 8 days) markedly inhibited the tumor growth accompanied by NAD+ depletion, TAX1BP1 distribution to mitochondria, AIF distribution to nuclei as well as DNA DSBs and PARP1 activation in tumor tissues." (PMID 37186123, 2023). "Furthermore, western blotting analysis revealed that the expression of CYLD, TAX1BP1 and OTUD7B dramatically decreased in the miR-500–overexpressing tumours but increased in miR-500–silenced tumours." (PMID 25595906, 2015).
bacterial infection (3 papers, 2024 to 2025). "Together, these results show that Tax1bp1 plays a crucial role in linking the regulation of autophagy, cell death, and pro-inflammatory host responses and enhancing susceptibility to bacterial infection." (PMID 39763950, 2024). "Galectin-8 binding partners were identified in murine macrophages during intracellular bacterial infection by IP-LC/MS, including autophagy-related proteins such as TAX1BP1 and ubiquitin, and lysosomal proteins and membrane trafficking proteins, including Rab7 and Rab14." (PMID 38395460, 2024). "Thus, Tax1bp1 has an anti-inflammatory function in several contexts, but the impact of Tax1bp1 in vivo during intracellular bacterial infection has hitherto not been described." (PMID 39763950, 2024).
neurodegenerative disease (1 paper, 2021). A disorder of the central nervous system characterized by gradual and progressive loss of neural tissue and neurologic function. "TAX1BP1 is highly and specifically expressed in the brain, and TAX1BP1 mediates clearance of a broad range of cytotoxic proteins, indicating its therapeutic potential in neurodegenerative diseases." (PMID 34440758, 2021).
TAX1BP1 also shares sentences with these, for which no sentence is quoted: lung carcinoma (2 papers); rheumatoid arthritis (2); acute myocardial infarction (1); autoimmune disease (1); B cell lymphoma (1); circulatory system diseases (1); clear cell carcinoma (1); COVID-19 (1); Hypertension (1); iron deficiency (1); schizophrenia (1).